TLR8 (toll like receptor 8)
Diseases named in the same sentence as TLR8 in open-access papers (continued):
Sharing a sentence is not in itself a finding about the gene and the disease.
breast carcinoma (9 papers, 2016 to 2025). "Increased TLR8 expression has been observed in breast cancer cell lines and tumor tissues compared to normal breast cells and tissues." (PMID 38903515, 2024). "It is important to note that the research on the role of TLR8 in breast cancer is relatively limited compared to some other TLRs, and further studies are needed to fully elucidate its mechanisms of action and potential therapeutic implications." (PMID 38903515, 2024). "Moreover, an ongoing clinical trial aiming at evaluating the HER2-targeted TLR7/TLR8 mixed agonist ISAC BDC-1001 is enrolling individuals with HER2+ breast cancer (NCT04278144)." (PMID 37063284, 2023). "Besides different subsets of CD4+ Treg cells, we found that the CD8+ Treg cells and γδ-TCR Treg cells in prostate and breast cancer also express a low level of human TLR8 molecules." (PMID 35309296, 2022). "Due to a lack of TLR family immunohistochemical samples, only TLR3, TLR4, TLR7, and TLR8 staining results in colorectal cancer, breast cancer, prostate cancer, and normal tissue were exhibited, which were largely consistent with the previously reported mRNA expression." (PMID 35801728, 2022). "Additionally, in breast cancer there are currently several clinical trials assessing efficacy of TLR7/8 agonists (TLR8, VTX-2337 and cyclophosphamide, NCT02650635; TLR7, imiquimod, cyclophosphamide, and radiotherapy)." (PMID 29190881, 2017). "Therefore, the interplay between TLR8 and TLR7, as well as their combined effects on breast cancer progression and immunity, require further investigation." (PMID 38903515, 2024).
malaria (9 papers, 2016 to 2025). Malaria is a serious and sometimes fatal disease caused by a parasite that commonly infects a certain type of mosquito which feeds on humans. "This study aimed to evaluate the association between polymorphisms in TLR1, TLR4, TLR7, TLR8, TLR9 and TIRAP and the clinical manifestations of malaria caused by P. vivax in a population from the Amazon region of Pará, Brazil." (PMID 40963451, 2025). "Testosterone pre-treatment amplifies TLR6 expression 5.6-fold and suppresses TLR8 expression 6.5-fold, suggesting dysregulated TLR6 and TLR8 signaling contributes to increased malaria susceptibility." (PMID 39492784, 2024). "Altogether, our data are the first reported activation of TLR8 by protozoan RNA and demonstrate both the critical role of TLR8 in human blood-stage malaria and its unique functionality in the human immune system." (PMID 30972055, 2019). "TLR8 is thought to prime and potentiate the inflammatory response to pathogens, thereby contributing to the pathogenesis of severe malaria." (PMID 26961973, 2016). "Therefore, this study aimed to analyse the potential influence of variants of TLR1, TLR4, TLR7, TLR8, TLR9 and TIRAP on the clinical manifestations of malaria caused by P. vivax in the Amazon region of Brazil." (PMID 40963451, 2025). "Here, future studies on the mechanisms of TLR8 signaling may prove crucial to the development of new therapies for malaria and bacterial infections." (PMID 30972055, 2019). "The TLR probes showed a higher expression in severe malaria cases during acute illness (2.07-fold for TLR2, 2.19-fold for TLR8, 2.27 and 2.46-fold for the TLR4 probes)." (PMID 26961973, 2016). "TLR probes showed a higher expression in severe malaria cases during acute illness (2.07-fold for TLR2, 2.19-fold for TLR8, 2.27 and 2.46-fold for TLR4 probes)." (PMID 26961973, 2016). "Differentially expressed probes form these canonical pathways that were previously shown to play a role in severe malaria pathogenesis were TLR2, TLR4, TLR8, HSPA6, CR1, C1qA, C1qB, C1qC, FOS, and GZMB." (PMID 26961973, 2016). "Of the remaining probes, four were in three genes, HSPA6, TLR8 and FOS, previously identified in experiments for malaria severity in human or murine systems." (PMID 26961973, 2016). "We provide evidence that TLR8 activation in human monocytes is essential for IFN-γ release from natural killer (NK) cells upon stimulation with PfRNA and iRBC, thus elucidating the PAMPs triggering early IFN-γ release in human malaria." (PMID 30972055, 2019). "Notably, complement genes (C1QA, C1QB, C1QC), apoptotic genes (PDL1, PDL2, APOL1, APOL2, FAS), inflammatory caspases (CASP1, CASP5), TLR pathway genes (TLR1, TLR4, TLR5, TLR8), cytokines (IL6, IL10), and granzyme (GZMB) were among the genes upregulated during symptomatic malaria." (PMID 39161730, 2024).
ischemic stroke (8 papers, 2013 to 2025). A stroke disorder caused by obstruction of blood flow to the brain, due to thrombotic (local blood clot formation) or embolic (due to a blood clot or other material traveling from another site) event. "Moreover, in whole blood of aging patients with ischemic stroke, it was observed that the TLR8 rs3764880 polymorphism is associated with the susceptibility to ischemic stroke in aging men." (PMID 35822020, 2021). "Recently, it was reported that TLR8 gene rs3764880 polymorphism might be associated with susceptibility and involved in the inflammatory response and lipid metabolism of ischemic stroke in southern Chinese Han population." (PMID 32746852, 2020). "The presence of several TLRs has been reported in the brain, both in glial and neuronal cells, and recent studies have reported the pathological roles of TLR2, TLR4 and TLR8 in ischemic stroke-induced brain injury." (PMID 25886362, 2015). "According to the results, TLR4, TLR7, and TLR8 are all involved in stroke, in which TLR4 and TLR8 have detrimental roles in ischemic stroke, while the activation of TLR7 can induce robust neuroprotection against stroke by triggering a novel type I interferon-mediated mechanism." (PMID 32565722, 2020). "Furthermore, the expression level of TLR8 correlated with poor outcome and increased inflammation in ischemic stroke." (PMID 23825649, 2013). "In addition, clinical studies have shown that the expression of TLR8 in the peripheral blood of patients with ischemic stroke is significantly related to the prognosis of patients, which proves the close connection between TLR8 and cerebral ischemia-reperfusion injury." (PMID 35008558, 2021). "However, the role of TLR8 in ischemic stroke is relatively rare." (PMID 32746852, 2020). "Additionally, clinical studies have shown that TLR8 expression in the peripheral blood of patients with ischemic stroke significantly correlated with the prognosis of the patients, which further demonstrates that TLR8 is directly involved in the inflammatory damage of cerebral ischemia and hypoxia." (PMID 25928750, 2015). "All four biomarkers (SRC, TLR8, FCAR, and HIF1A) were significantly upregulated in ischemic stroke patients compared to healthy controls." (PMID 40948644, 2025).
ovarian carcinoma (8 papers, 2020 to 2024). A malignant neoplasm originating from the surface ovarian epithelium. "Inhibition of CD4+ Tregs’ ability to suppress the immune system by TLR8 (Toll like receptor 8) is also correlated with glucose metabolism in ovarian cancer." (PMID 38292487, 2023). "This phase II trial (NCT01666444) investigated the combination of the toll-like receptor 8 (TLR8) agonist motolimod with ICD-inducing chemotherapeutic pegylated liposomal doxorubicin in women with recurrent or persistent ovarian cancer." (PMID 34497771, 2021).
Sepsis (8 papers, 2014 to 2025). Sepsis is defined as life-threatening organ dysfunction caused by a dysregulated host response to infection. "In a previous study, we showed that viral kshv-miR-K12-12* was upregulated in patients with sepsis and acted as a direct agonist of TLR8, contributing to the pathophysiology of sepsis." (PMID 37261908, 2023). "Among the genes identified through the PPI network, many genes such as MPO, CD28, and TLR8 have been reported to play a vital role in sepsis." (PMID 35739592, 2022). "Increased miR-K-10b and miR-K12-12* are functionally involved in sepsis as agonists of TLR8, forming a positive feedback that may lead to cytokine dysregulation." (PMID 25476907, 2014). "In addition, we showed that both endogenous miRNAs, and also viral miRNAs that can bind TLR8, are altered in sepsis, that miRNA networks in sepsis are reorganized, and that the same sepsis-related miRNAs are dysregulated after splenectomy, a condition that increases the risk of sepsis." (PMID 37261908, 2023). "Thus, TLR8 and type I IFN might play a protective role in sepsis caused by GBS and other streptococci." (PMID 29042860, 2017). "Indeed, he showed data on the differential expression of viral miRNAs in the plasma of patients early post-surgery and in sepsis in comparison with healthy volunteers and their functional involvement in sepsis acting as agonist of TLR8 in a positive feedback that may lead to cytokine dysregulation." (PMID 30867009, 2019).
systemic sclerosis (8 papers, 2017 to 2025). A chronic disorder, possibly autoimmune, marked by excessive production of collagen which results in hardening and thickening of body tissues. "TLR8 is a key player in the pathogenesis of systemic Sclerosis (SSc) due to its aberrant expression in pDCs from SSc patients and its ability to exacerbate disease in mouse model of scleroderma." (PMID 33498655, 2021). "Recent findings on systemic sclerosis reported the abnormal expression of TLR8 in pDCs that leads to IFN-α production suggesting a key pathological role of RNA-sensing TLR involvement in the establishment of fibrosis." (PMID 33262343, 2020). "It has been reported that pDCs contribute to skin fibrosis in systemic sclerosis largely through activation of TLR8." (PMID 31093508, 2019). "In addition, the ectopic expression of TLR8 on pDCs in systemic sclerosis patients induces the production of CXCL4, which in turn enhances TLR8- and TLR9-induced IFN production by pDCs." (PMID 35309296, 2022).
colitis (7 papers, 2018 to 2025). Inflammation of the colon. "TLR-4 and TLR-8 expression increased significantly in response to both C. albicans overgrowth and colitis while treatment with DHMB decreased the expression of these receptors in the colons." (PMID 30646601, 2019). "Notably, knockout studies of BID and TLR8 in mice resulted in increased colitis and intestinal inflammation, supporting their association with decreased local inflammation as suggested by our IPA analysis." (PMID 40255128, 2025). "Interestingly, the levels of TLR4 and TLR8 gene expression were previously increased when acute colitis was induced in pigs that had received a microbiota transplant from one pig breed but not another." (PMID 29577087, 2018). "Chitin treatment increased chitinase-3-like protein-1, enabling chitin digestion and the generation of small sized chitin particles that induced IL-10 production via PPARg, NOD-2, and TLR-8 sensing, promoting the attenuation of colitis and C. glabrata elimination." (PMID 29463799, 2018). "It is known that TLR8 activation can enhance TNF and IL-1β production, both associated with mucosal inflammation in UC, whereas TLR7 agonists could induce a type I IFN response and prevent experimental colitis in mice." (PMID 37446274, 2023). "Additionally, oral administration of chitin in the DSS-induced colitis model reduced the number of aerobic bacteria and proliferation of C. glabrata, and decreased the impact of colitis mediated by the expression of TLR-8, dectin-1 and PPARγ and anti-inflammatory mediators." (PMID 35630457, 2022). "In a dextran sulfate sodium-induced colitis model, oral administration of fungal chitin reduced the inflammatory parameters and leukocyte infiltration into the gut mucosa and increased IL-10 production via stimulation of NOD-2 and TLR8." (PMID 31781518, 2019).
neutropenia (7 papers, 2021 to 2026). A decrease in the number of neutrophils found in the blood. "Conversely, gain-of-function mutations of TLR8 causes inborn errors of immunity characterized by neutropenia, antibody deficiency, and lymphoproliferation." (PMID 40910948, 2026). "Gain-of-function mutations in the TLR8 gene such as P432L, F494L, and G527D, cause neutropenia, infections, lymphoproliferation, and B cell deficiency." (PMID 35812450, 2022). "The consistent refractory neutropenia with lymphoproliferation makes patients with TLR8 variant a unique entity among IEI." (PMID 33864184, 2021). "Patients with TLR8 GOF were all relatively refractory to standard therapy for neutropenia, including G-CSF treatment." (PMID 34199501, 2021). "We identified six unrelated boys with neutropenia, B cell defects, and lymphoproliferation, all with novel genetic variants in TLR8, the gene encoding toll-like receptor 8 (TLR8), an endosomal TLR that recognizes single-stranded RNA." (PMID 33864184, 2021). "Recently, we described germline and somatic variants in TLR8 as an underlying monogenic cause of IEI in patients with recurrent infections, neutropenia, lymphoproliferation, hypo-gammaglobulinemia, and bone marrow failure." (PMID 34199501, 2021). "The TLR8-GOF patients nearly universally showed the variant in all nucleated blood cells, including lymphocytes (T-, B-, and Natural Killer (NK) cells), as well as monocytes (keeping in mind neutropenia in patients)." (PMID 36119097, 2022). "In contrast to human patients harboring gain-of-function mutations in the TLR8 gene, neither neutropenia nor B cell deficiency was observed." (PMID 35812450, 2022). "Concentrated in its most essential ingredients, TLR8-GOF is a genetic disorder with autoimmune cytopenias, infections, lymphoproliferation, and neutropenia." (PMID 36119097, 2022).
Alzheimer disease (6 papers, 2018 to 2025). A progressive, neurodegenerative disease characterized by loss of function and death of nerve cells in several areas of the brain leading to loss of cognitive function such as memory and language. "Using a machine learning algorithm and the disease-linked database PhenoMiR, we identified Alzheimer’s disease (AD)- and glioma-associated miRNAs as ligands for TLR7 and TLR8." (PMID 41322409, 2025). "Intriguingly, a recent paper indicates a potential new function of HERV-K transcripts in neurodegeneration, via trigger TLR7 and TLR8 signaling in a mouse model of Alzheimer’s disease." (PMID 36451209, 2022). "Here again, both beneficial and detrimental roles were attributed to TLRs and for instance TLR7, TLR8 and TLR9 signaling could enhance microglial amyloid beta uptake in the early stage of Alzheimer’s disease, but over time contribute to sustained neuroinflammation." (PMID 34335238, 2021).
colorectal cancer (6 papers, 2014 to 2025). A primary or metastatic malignant neoplasm that affects the colon or rectum. "Our previous study indicated that endosomally expressed TLR7 and TLR8 are associated with tumor progression in colorectal cancer and reduced tumor-specific survival amongst patients with high TLR7 and TLR8 expression in colorectal cancer cells." (PMID 26134824, 2015). "Moreover, our results indicated that both TLR7 and TLR8 expression is associated with tumor progression in patients with colorectal cancer and reduced tumor-specific survival among patients with high TLR7 and TLR8 expression in their cancer cells." (PMID 26134824, 2015). "We previously reported that TLR7 and TLR8 expression is upregulated in tumor cells of patients with colorectal cancer." (PMID 26134824, 2015). "TLR8 expression increased the chemotherapy resistance in colorectal cancer." (PMID 35204406, 2022). "Colorectal cancer tissues have higher TLR1, TLR2, TLR4 and TLR8 gene expression levels in general than do the normal colon mucosa from the same patient (p < 0.05)." (PMID 25547486, 2014).
glomerulonephritis (6 papers, 2013 to 2024). A renal disorder characterized by damage in the glomeruli. "Female 564Igi Tlr7/9−/− mice with two normal X chromosomes, and hence two functional copies of Tlr8, produce autoantibodies, express Ifn-I in neutrophils, have expanded populations of granulocytes, and ultimately develop glomerulonephritis." (PMID 26441962, 2015). "In conclusion, the overexpression of TLR8 correlates with the progression of podocyte injury in glomerulonephritis." (PMID 25468389, 2014). "However, TLR8 deletion of C57BL/6 genetic background triggers anti-dsDNA antibody secretion and glomerulonephritis, an effect abrogated by co-deletion of TLR7 suggesting rather an immunoregulatory role of TLR8 in TLR7." (PMID 29650017, 2018). "Notably, mouse models with a TLR8 deletion develop glomerulonephritis, but this effect is absent when both TLR7 and TLR8 are deleted." (PMID 39835128, 2024).
non-small cell lung carcinoma (6 papers, 2017 to 2025). A group of at least three distinct histological types of lung cancer, including non-small cell squamous cell carcinoma, adenocarcinoma, and large cell carcinoma. "In 2012, it was demonstrated that EVs containing miR-21 and miR-29a released by non-small cell lung cancer cell lines were targeting tumor-associated macrophages and, more specifically, the human toll-like receptor 8 (TLR8), triggering the downstream pathway." (PMID 30884898, 2019). "Further, it has been demonstrated that exosomal-secretion of miRNA can affect the tumor microenvironment through interactions with TLR8 in non-small cell lung cancer and neuroblastoma, which was implicated in cisplatin-resistance for the latter." (PMID 29137278, 2017). "Indeed, tumour cell-intrinsic expression of TLR7 and TLR8 promotes their growth and survival in vitro and is associated with poor clinical outcome in non-small cell lung carcinomas (NSCLC)." (PMID 40336011, 2025). "TLR7 and TLR8 activation in non-small cell lung cancer induced survival of cancer cell lines and increased cancer cell chemoresistance." (PMID 38709790, 2024). "TLR4, TLR5, TLR7, and TLR8 were more highly expressed in non-small cell lung cancer (NSCLC)." (PMID 41471188, 2025).
AIDS (5 papers, 2012 to 2023). A syndrome resulting from the acquired deficiency of cellular immunity caused by the human immunodeficiency virus (HIV). "The TLR8 variants with weak activity are related to slow decrease of CD4+ T cell and clinical progression of AIDS in HIV-1 infected individuals." (PMID 37134013, 2023). "The expression of TLR8 was significantly decreased in subjects with AIDS compared with both uninfected subjects and SPs (p = 0.0414, p = 0.0169)." (PMID 22243920, 2012). "Taken together, expression of TLR7 and TLR8 in monocytes was correlated with AIDS disease progression and appeared to decrease as with advancing severity of disease from SPs to AIDS." (PMID 22243920, 2012). "TLR7 expression was decreased significantly at each subsequent stage of HIV infection, while TLR8 expression decreased significantly from baseline levels only at the AIDS stage." (PMID 22243920, 2012). "Indeed, we found that TLR7 and TLR8 expression levels in monocytes declined as a function of the severity of HIV infection (i.e. slow progression to chronic HIV infection to AIDS)." (PMID 22243920, 2012). "On the other hand, activation of PRR pathways such as TLR2 and TLR4 may lead to inflammation, promoting HIV replication and accelerating the progression of AIDS, while TLR7 and TLR8 may increase the expression of NF-κB, inhibiting HIV replication and delaying the progression of AIDS in ECs/LTNPs." (PMID 35211115, 2022).